POSTN (periostin)
Diseases named in the same sentence as POSTN in open-access papers (continued):
Sharing a sentence is not in itself a finding about the gene and the disease.
myeloma (5 papers, 2007 to 2023). "Serum periostin is also elevated in myeloma patients at first relapse and in patients at the plateau phase of the disease after frontline therapy." (PMID 27716740, 2016). "Even patients at the plateau phase of the myeloma had elevated periostin levels in their serum compared with healthy controls." (PMID 27716740, 2016). "Beside the experimental data, the authors investigated periostin in clinical settings and found the progressive elevation of its levels as the disease evolves from MGUS, SMM (smoldering multiple myeloma), and symptomatic MM." (PMID 38067265, 2023). "In conclusion, sRANKL, periostin, and osteopontin reflect MBD severity and could be promising markers for MBD monitoring and the effect of myeloma treatment." (PMID 38067265, 2023). "No specific staining for periostin was noted in Langerhans cell histiocytosis, Ewing sarcoma, lymphoma, myeloma, chordoma or adamantinoma." (PMID 30202513, 2018). "Of interest, the levels of periostin did not increase after incubation of myeloma cell lines with the stromal cell line HS5 after 24 or 48 h, suggesting that the production of periostin by the myeloma cell lines is not dependent on the stromal cells." (PMID 27716740, 2016). "However, there is no information on the role of periostin in multiple myeloma (MM)." (PMID 27716740, 2016). "After incubation for 24 and 48 h with stromal cell line HS5 (periostin level in the HS5 supernatant was 0.227 ng/ml), there was no alteration in the periostin levels of the supernatants of the myeloma cell lines." (PMID 27716740, 2016).
nasopharyngeal carcinoma (5 papers, 2014 to 2022). A carcinoma arising from the nasopharyngeal epithelium. "Overexpression of periostin in nasopharyngeal carcinoma stroma was then found to be associated with advanced clinical stage." (PMID 24713112, 2014). "Laser-capture microdissection was used to assess proteomic changes in the stroma of nasopharyngeal carcinoma, resulting in the identification of periostin as a protein that is upregulated in these carcinoma cells when compared to normal nasopharyngeal tissue." (PMID 24713112, 2014). "Using IHC, the majority of periostin was detected in the stroma of nasopharyngeal carcinoma (NPC), the DCIS and the IBC." (PMID 36224629, 2022). "(2020) reported top three hub genes of PPI network of FANCI, POSTN, IFIH1, ZMYND10, PACRG and POU2AF1 for nasopharyngeal carcinoma biomarkers using STRING database PPI network construction with MCODE for module analysis." (PMID 36299526, 2022).
oesophageal cancer (5 papers, 2011 to 2024). "Genetic ablation of the periostin gene (POSTN) in the CAFs eliminates the pro-invasive effects on the oesophageal cancer cells." (PMID 27515461, 2016). "Recently, periostin was found to promote invasiveness of esophageal carcinoma." (PMID 21611158, 2011). "Moreover, the secretion of periostin by these oesophageal CAFs bind to αvβ3 and αvβ5 on oesophageal cancer cells activating PI3 kinase signalling and promoting oesophageal cancer cell invasion." (PMID 27515461, 2016).
polyp (5 papers, 2015 to 2021). A usually exophytic mass attached to the underlying tissue by a broad base or a thin stalk. "Periostin was heterogeneously distributed among these cross sections, with positive staining most evident at the lateral margin of polyps, although periostin‐positive staining was also occasionally found in the interstitium of polyp parenchymal tissues." (PMID 31210032, 2019). "Further, we found that the polyp tissues from the ENP group exhibited significantly higher periostin and VEGF mRNA and protein levels than those from the nENP group and control subjects." (PMID 28842563, 2017). "From tissue expression, in vitro mouse models, Sang-Wook teams investigated the relationship between periostin expression and polyp lesion formation and infiltration and found the role of periostin might appear a protective in the development of ECRS." (PMID 32954441, 2021). "In accordance with above studies, in ECRS patients, high expressions could promote the levels of periostin and simultaneously aggravate tissue remodeling process, which can lead more structure changes, such as polyp formation." (PMID 32954441, 2021). "Their results also demonstrated that the polyp recurrence rate was significantly higher in patients with a high serum periostin level, which indicated that the preoperative serum periostin level could be a clinical marker for recurrence after surgery." (PMID 33218117, 2020).
Pruritus (5 papers, 2022 to 2024). Pruritus is an itch or a sensation that makes a person want to scratch. "Periostin is an extracellular matrix protein closely related to Th2 immune response with an emerging role in pruritus and barrier dysfunction." (PMID 36993985, 2023). "The discovery of Hashimoto provided a new direction for researching the mechanism of Periostin-mediated pruritus in PS through the activation of TRPV1 and TRPA1." (PMID 37705977, 2023). "Through perturbed periostin homeostasis, fibroblasts could therefore play a key role in pruritus pathology." (PMID 36385768, 2022). "Based on the available literature, eosinophils, IgG autoantibodies, IgE autoantibodies, SP and its receptor NK1R, IL-31 and its receptor OSMRb, IL-31RA, IL-13, IL-4, periostin, and basophils may be responsible for pruritus in BP and could be potential therapeutic targets." (PMID 39459488, 2024). "Within group 1 of patients, HDM-induced IL-31 response directly correlated with pruritus (r = 0.67, p = .0036) and plasma levels of CCL27 (r = 0.62, p = .0090) and periostin (r = 0.56, p = .050)." (PMID 36993985, 2023). "In group 1, compared with group 2, HDM-induced IL-31 in CLA+ T cells positively correlated with patient ́s pruritus intensity, and plasma levels of CCL27 and periostin." (PMID 36993985, 2023). "A correlation between IL-31 production and patient’s pruritus intensity, plasma CCL27 and periostin was detected." (PMID 36993985, 2023). "Periostin is produced by TGF-β1 and histamine-stimulated FBs and induces pruritus by binding to the aVb3 integrin receptor or inducing the Th2 cytokine cascade." (PMID 37705977, 2023). "Dermal periostin is upregulated in patients with both AD and prurigo nodularis (PN, a chronic, inflammatory skin condition characterized by itchy nodules), and also induces allergic itch in mice, dogs and non-human primates via integrin αVβ3." (PMID 36385768, 2022).
Renal cyst (5 papers, 2017 to 2025). A fluid filled sac in the kidney. "Knowing that periostin protein level is increased in MMP9 deficient kidney compared to control cystic kidney, we next aimed to understand whether the accumulation of this protein contributes to the severity of the kidney disease observed in mice lacking MMP9." (PMID 38039285, 2023). "Elevated periostin levels in children with persistent renal cysts likely indicate ongoing reparative and fibrotic processes within dysplastic parenchyma." (PMID 41156134, 2025). "Further research has demonstrated that periostin overexpression in collecting ducts accelerates renal cyst growth and fibrosis." (PMID 39728072, 2024). "Periostin can also participate in the proliferation of renal cyst cells through the Periostin-ILK-AKT-mTOR signal axis." (PMID 33241962, 2020). "In patients with the renal cysts, the cut-off value of periostin was 133.57 ng/mL." (PMID 41156134, 2025). "We next investigated the location of periostin and MMP9 in control cystic kidney." (PMID 38039285, 2023).
triple-negative breast carcinoma (5 papers, 2012 to 2025). An invasive breast carcinoma which is negative for expression of estrogen receptor (ER), progesterone receptor (PR), and human epidermal growth factor receptor 2 (HER2). "For instance, POSTN short fragment with exon 17 promotes EMT and metastasis, while POSTN exon 21 antibodies inhibit tumor cell growth by reducing macrophage M2 polarization and the number of tumor blood vessels in triple-negative breast cancer." (PMID 41018265, 2025). "In triple-negative breast cancer xenografts, chemotherapy upregulated periostin expression in tumor cells, triggered expansion of mesenchymal tumor cells and promoted invasion in residual tumors." (PMID 29507310, 2018). "Moreover, 133 (45.08%) of the 295 triple-negative breast cancers showed periostin expression compared to 201 (25.74%) of the 781 cases of non-triple-negative breast cancers (P = 0.001)." (PMID 23056395, 2012). "Given that the involvement of periostin in cancer stem cell functions, metastasis and chemoresistance is observed in other human cancers, this strategy could prove to be effective in overcoming chemoresistance beyond triple-negative breast cancer." (PMID 29507310, 2018). "Together, these data indicate that periostin plays a key role in EMT-dependent chemoresistance and is a promising target to overcome chemoresistance in triple-negative breast cancer." (PMID 29507310, 2018). "Spearman correlation regression analysis showed that periostin expression has a linear correlation to histological grade, CSC ratio, lymph node metastasis, tumor size and triple-negative breast cancer (P = 0.001, 0.001, 0.001, 0.001, and 0.001 respectively)." (PMID 23056395, 2012).
cervical carcinoma (4 papers, 2020 to 2025). A carcinoma arising from either the exocervical squamous epithelium or the endocervical glandular epithelium. "Functional validation further indicated that the silencing of MMP3 and POSTN significantly impedes the proliferation and migration of cervical cancer cells." (PMID 40747615, 2025). "Through proteomic analysis and immunostaining, the first evidence is provided that POSTN is overproduced in the PM SLN of patients with early cervical cancer." (PMID 35567669, 2022). "Using transcriptome analysis, we found two potential predictive biomarkers (APOBE3A and POSTN) for recurrent/ metastatic cervical cancer." (PMID 33017516, 2020). "An additional finding of interest relies on the fact that POSTN could be a potential marker of cervical cancer progression by its expression in early stages of the metastatic cascade and its association with lymphatic vessels." (PMID 35567669, 2022). "Transcriptional upregulation of POSTN expression was significantly associated with poor OS rate and DFS rate (P‐value = .001 and .043, respectively, log‐rank test), indicating that POSTN may serve as a prognostic biomarker for metastatic cervical cancer." (PMID 33017516, 2020). "This study constructed a cervical cancer prognosis model based on MPT‐driven necrosis‐related genes (ICOS, MMP3, POSTN) by integrating single‐cell and transcriptomic data." (PMID 40747615, 2025). "In agreement, the expression levels of the extracellular protein periostin and MALAT1 were found to be negativity correlated with the expression of miR-202-3p in cervix carcinoma tissues." (PMID 35682549, 2022). "Elevated POSTN and reduced APOBEC3A at transcription level correlated with unfavorable cervical cancer clinical outcomes." (PMID 33017516, 2020). "We here identified periostin (POSTN) as a component of non-metastatic LNs by applying proteomic analyses and computerized image quantifications on LNs of patients with cervical cancer." (PMID 35567669, 2022).
COVID-19 (4 papers, 2022 to 2024). A disease caused by infection with severe acute respiratory syndrome coronavirus 2. "Moreover, serum periostin was also linked to fibrogenesis in COVID-19." (PMID 36611844, 2022). "To examine this further, we measured the ventricular expression of FAP and POSTN in COVID-19 samples with PMI less than 8 hours (PMI criteria used for snRNA-Seq analysis)." (PMID 34905515, 2022). "Consequently, it is plausible that the virus can elicit an augmented secretion of TGF-β, either directly or indirectly, by activating periostin in fibroblasts and basal keratinocytes during both the acute and protracted phases of COVID-19." (PMID 38399677, 2024). "Moreover, periostin was localized to fibroblastic foci in IPF lungs and in similar structures within post-COVID-19 lung tissue." (PMID 39767799, 2024). "Periostin of bronchoalveolar lavage fluid (BALF) might exaggerate the onset of eosinophilic pneumonia (EP), IPF, and COVID-19." (PMID 36611844, 2022). "In the microthrombi-positive COVID-19 samples, myocardial expression of POSTN was nonsignificantly increased relative to that in microthrombi-negative samples." (PMID 34905515, 2022). "Expanded analysis of all COVID-19 samples with PMI less than 24 hours demonstrated similar results; microthrombi-positive samples expressed nonsignificantly higher levels of POSTN and similar levels of FAP as microthrombi-negative samples." (PMID 34905515, 2022).
diabetic cardiomyopathy (4 papers, 2015 to 2023). Diabetic cardiomyopathy is a disorder of the heart muscle in people with diabetes. "Periostin is an extracellular matrix protein that plays a critical role in cell fate determination and tissue remodeling, but the underlying role and mechanism of periostin in diabetic cardiomyopathy (DCM) are far from clear." (PMID 37993768, 2023). "More study is needed to demonstrate if there is any relationship between FFA-metabolism and periostin on diabetic cardiomyopathy." (PMID 26281830, 2015). "The aim of the present study was to observe the expression of periostin in Wistar rat’s myocardium of diabetic cardiomyopathy (DCM) and the effect of valsartan on it." (PMID 26281830, 2015).
dilated cardiomyopathy (4 papers, 2017 to 2023). Cardiomyopathy which is characterized by dilation and contractile dysfunction of the left and right ventricles. "Higher serum periostin level was related to increased composite cardiovascular events, and circulating periostin was higher in patients with severe dilated cardiomyopathy and correlated to the degree of diastolic dysfunction." (PMID 36369212, 2022).
Duchenne muscular dystrophy (4 papers, 2021 to 2026). Duchenne muscular dystrophy (DMD) is a neuromuscular disease characterized by rapidly progressive muscle weakness and wasting due to degeneration of skeletal, smooth and cardiac muscle. "Thus, we crossed periostin-null mice with mdx mice, a mouse model of Duchenne muscular dystrophy, and analyzed the muscle weight of offspring." (PMID 33807264, 2021). "Subsequent in vivo studies in the D2.mdx mouse model of Duchenne muscular dystrophy (DMD) demonstrated that our antisense treatment effectively reduced e17+ Periostin mRNA expression, which coincided with reduced full-length Periostin protein expression and collagen accumulation." (PMID 38892298, 2024).
endothelial dysfunction (4 papers, 2012 to 2025). In vascular diseases, endothelial dysfunction is a systemic pathological state of the endothelium (the inner lining of blood vessels) and can be broadly defined as an imbalance between vasodilating and vasoconstricting substances produced by (or acting on) the endothelium. "In contrast, the 2D hPSC-ECs and HMVEC-Cs upregulated genes associated with LECs and, alongside 3D hPSC-ECs, expressed genes implicated in endothelial dysfunction (KALRN, POSTN, FN1, respectively)." (PMID 38775849, 2024). "Consequently, these findings indicate that COL1A1, COL3A1, and POSTN could potentially be used as biomarkers to assess the severity of endothelial dysfunction in the progression of ED." (PMID 38467692, 2024).
eosinophilic esophagitis (4 papers, 2010 to 2022). Eosinophilic esophagitis (EoE) is a chronic, allergic disease of the esophagus characterized clinically by symptoms of esophageal dysfunction (including vomiting, dysphagia, feeding disorders, food impaction and abdominal pain) which persist after treatment with proton pump inhibitors (PPIs). "In eosinophilic esophagitis (EOE), compared with control groups, they found there was overexpression of periostin in esophageal tissues obtained from EOE patients." (PMID 32954441, 2021).
gingivitis (4 papers, 2020 to 2025). A disorder involving inflammation of the gums; may affect surrounding and supporting structures of the teeth. "In the studies of Balli U and Sophia K, the amount of periostin in the GCF of the gingivitis group is significantly lower than that of the healthy group." (PMID 37173720, 2023).
glomerulonephritis (4 papers, 2017 to 2024). A renal disorder characterized by damage in the glomeruli. "Moreover, we have recently demonstrated that periostin is induced by NFκB and other pro-inflammatory transcription factors in experimental glomerulonephritis." (PMID 28536691, 2017). "Therefore, it is reasonable to believe that the positive feedback regulation between periostin and TGF-β may play a key role in EMT, and abnormal overexpression of periostin would lead to glomerulonephritis and interstitial fibrosis and cause persistent damage to the kidney in DN." (PMID 34992536, 2021). "The deletion of the periostin gene resulted in a significant reduction of pro‐inflammatory mediators, preserving renal structure and function in an animal model of nephrotoxic serum (NTS)‐induced glomerulonephritis." (PMID 39570100, 2024). "In addition, periostin inhibition by antisense oligonucleotides delays and in some cases reverses the progression of CKD in hypertensive and glomerulonephritis animal models." (PMID 35883655, 2022).
glomerulosclerosis (4 papers, 2013 to 2022). A hardening of the kidney glomerulus caused by scarring of the blood vessels. "Periostin is known to play a role in glomerulosclerosis and renal interstitial fibrosis, both entities are associated with aging." (PMID 23947592, 2013). "Proteins important in glomerular sclerosis or inflammation seem to be most strongly increased and periostin might be an important marker of glomerular damage in IgAN." (PMID 31726998, 2019). "Moreover, inhibition of periostin expression using antisense oligonucleotides ameliorated glomerulosclerosis in L-NAME-induced renal injury model mice." (PMID 28819200, 2017).
hepatoblastoma (4 papers, 2019 to 2022). Hepatoblastoma (HB) is a malignant hepatic tumor and is the most common pediatric liver cancer. "In CCA and hepatoblastoma, overexpressed periostin was found to induce cell migration and epithelial-to-mesenchymal transition (EMT) features." (PMID 32293552, 2020). "Periostin (POSTN)-induced hepatoblastoma cells undergo EMT, mediated by the mitogen activated protein kinase (MAPK)/extracellular signal regulated kinase (ERK) pathway." (PMID 31547062, 2019). "Therefore, POSTN has potential as a therapeutic biomarker for hepatoblastoma." (PMID 35057799, 2022). "We identified high levels of IGF2 in patients enriched for Hepatoblastoma I and Hepatoblastoma II signatures, GATA1 in patients enriched for the Erythroid-like signature, POSTN in patients enriched for the DCN-high signature, and CHGA in patient 8 who was enriched in the Neuroendocrine signature." (PMID 36008377, 2022).
hypertriglyceridemia (4 papers, 2016 to 2021). A laboratory test result indicating elevated triglyceride concentration in the blood. "In livers, Postn expression is elevated in obese mice and humans, and overexpression of periostin in mouse livers promoted hepatic steatosis and hypertriglyceridemia." (PMID 30088333, 2018).
inflammatory skin disease (4 papers, 2018 to 2023). Inflammatory skin disorders covers a broad category that includes many conditions ranging in severity, from mild itching to grave medical health complications These disorders are common in people of all ages and races. "An elevated periostin level in these inflammatory skin diseases is a result of dysregulated immune responses." (PMID 36598904, 2023).